NRAS (NRAS proto-oncogene, GTPase)
Diseases named in the same sentence as NRAS in open-access papers (continued):
Sharing a sentence is not in itself a finding about the gene and the disease.
tumor (continued). "RMC-7977, a compound that exhibits potent inhibition of the active states of mutant and wild-type KRAS, NRAS and HRAS variants has a strong anti-tumour effect on RAS-addicted tumours and is well tolerated in preclinical models." (PMID 38589574, 2024). "For example, let-7c is thought to act as a tumor suppressor in various cancers, including PCa, by targeting genes like NRAS and c-Myc." (PMID 39796656, 2024). "This synergy appears to be important for reaching the desired effects in NRAS mutant tumors, with a combination of Cobimetinib and Belvarafenib outperforming single-agent Belvarafenib at suppressing tumor growth." (PMID 39199684, 2024). "The primary tumor and lymph node lesions demonstrated the presence of NRAS G12C MT, although the MAF was close to the test’s cutoff value (primary average MAF: 5.0%, lymph node MAF: 1%) according to whole-exome tissue sequencing." (PMID 39003289, 2024). "Tumor mutation status was assessed and found to be BRAF wildtype and mutated in the NRAS gene, in Q61R." (PMID 39148899, 2024). "We identified 4 MSI-high samples, 39 KRAS/NRAS mutations, and 5 BRAF p.V600E mutations, with one case of coexistence of all three markers in a single tumor sample." (PMID 38539463, 2024). "There are frequent genomic alterations in these neoplasms, especially in the mitogen-activated protein kinase pathway, including BRAF (notably BRAF V600E), MAP2K1, KRAS, and NRAS mutations, and ALK gene translocation." (PMID 38713245, 2024). "We assessed the concordance level for NRAS and BRAF mutations between each LB analyte and the tumor tissue since these two genes are commonly screened in clinical routine." (PMID 38898234, 2024). "Among MM drivers, somatic mutations of NRAS and the TERT promoter are reported, as well as mutually exclusive loss of function mutation of the tumor suppressors NF1 and SPRED1, the latter co-occurring with activating KIT mutations." (PMID 38191367, 2024). "To further explore the ability of Mb24 to inhibit oncogenic NRAS function, we tested the effect of Mb24 on the anchorage-independent growth and migration of NRAS-mutant tumor cells." (PMID 39379700, 2024). "NCCN guidelines recommend the evaluation of tumor gene status, including KRAS/NRAS and BRAF mutations, as well as HER2 amplification and microsatellite instability (MSI)/mismatch repair (MMR) status, for the systemic treatment of advanced or mCRC45." (PMID 38172565, 2024). "NRAS also promotes the colonization of the lungs by various tumor types in mouse models by regulating interleukin-8-related chemokine expression." (PMID 39507527, 2024). "We performed Cox regression to examine the signature’s independence from additional clinical characteristics (age, breslow depth, gender, tumor stage, and BRAF and NRAS mutations) in the TCGA cohort." (PMID 38874871, 2024). "Consistent with the scRNA-seq data, the ectopic NRAS level tended to be higher in the NOTCH1/nestin+ tumours." (PMID 39112713, 2024). "To visualize the model, we plotted a nomogram based on six independent factors (sex, HT, tumor size, extrathyroidal extension, TERT promoter mutations and NRAS mutation) in the training cohort." (PMID 36817603, 2023). "In vivo combination of trametinib with BCL-2 inhibitors led to tumor inhibition in NRAS-mutant and NF1-deleted xenografts." (PMID 36895472, 2023).
tumor (continued). "Tumours demonstrating the MaP pattern of stromal invasion more frequently harboured core MAPK pathway mutations (KRAS, BRAF, NRAS)." (PMID 37169775, 2023). "Within the training cohort, univariable analysis demonstrated that sex, HT, tumor size, tumor number, extrathyroidal extension, BRAF mutation, TERT promoter mutations and NRAS mutations were relative influencing factors of CLNM (P<0.05)." (PMID 36817603, 2023). "CLNM in cN0 PTMC patients is associated with male sex, tumor size, extrathyroidal extension, HT, TERT promoter mutations and NRAS mutation." (PMID 36817603, 2023). "In the case of a multiorgan pattern of relapse, patients were evaluated for the presence of targetable tumor DNA mutations (eg, BRAF, NRAS, and NF1)." (PMID 36852837, 2023). "Furin mRNA was significantly higher in tumours from male patients, tumours that were wild -type for the NRAS gene, and tumours that presented lymph node metastasis." (PMID 37568724, 2023). "In what follows, we provide more detailed information on two exemplary cases, namely, the first oncogene (NRAS) and the first tumor-suppressor (VHL) featured in this ranking." (PMID 37834310, 2023). "The variables taken into consideration are BRAF, KRAS, NRAS mutations, the expression of fibronectin, CXCR4, and FAP in terms of intensity in both the primary tumor and metastases, and the number of metastases." (PMID 37892020, 2023). "In the present study, we investigated the prognostic value of the mutational status of the KRAS, NRAS, PIK3CA and BRAF genes detected in tumor biopsies and plasma samples from 51 synchronous metastatic colorectal cancer (SMCC) patients." (PMID 37176143, 2023). "The highest frequency of mutations detected was in the KRAS gene, in tumor biopsies and plasma samples, followed by mutations of the PIK3CA, NRAS and BRAF genes." (PMID 37176143, 2023). "By inspecting their oncoprint, 27/59 tumours harboured mutations in either SOX9 or MYC and were wild-type in either BRAF, KRAS or NRAS, hinting towards an alternative cetuximab resistance mechanism." (PMID 37666855, 2023). "RAS mutations are long known to provide radiation resistance to tumor cells, as demonstrated first in mouse cell lines transformed with HRAS, NRAS or KRAS mutations." (PMID 37907934, 2023). "This tumour-suppressive mechanism was dependent on the differential activation of YAP/TAZ signalling between tumour and normal hepatocytes and was sufficient to also eliminate NRAS-mutant melanoma metastases from the liver." (PMID 36175301, 2023). "At molecular analysis of KRAS and NRAS in FFPE tumor tissue biopsies, 41 out of 62 patients (66.1%) harbored RAS mutations, while 21 (33.9%) were classified as WT." (PMID 37296579, 2023). "Tumours of colorectal cancer patients were shown to exhibit, for instance, either KRAS or NRAS mutations (referred to as RAS mutations) with a rate of about 50%, which tend to occur mutually exclusive." (PMID 37666855, 2023).
tumor (continued). "The results showed that sex, HT, tumor size, extrathyroidal extension, TERT promoter mutations and NRAS mutation were independent factors." (PMID 36817603, 2023). "The post-operative pathology identified adenocarcinoma (pT4N2cM1) with KRAS/NRAS/BRAF wild-type MSS status in her tumor." (PMID 37681031, 2023). "The results revealed six independent factors, of which male sex, increased tumor size, extraglandular infiltration, TERT promoter mutations and NRAS mutation increased the risk of CLNM, while HT was a protective factor (P<0.05)." (PMID 36817603, 2023). "BRAF, NRAS, TG, TTN, and HRAS were the most frequently mutated genes in the early and late stages of the tumor; however, other genes were found to be more frequently mutated in the late stage." (PMID 37854594, 2023). "The two groups were compared for variables of age, gender, tumor location, histology, depth of tumor invasion, lymph node metastasis, lymph invasion, venous invasion, distant metastasis, CEA level, and KRAS, NRAS, and HRAS mutations." (PMID 37758931, 2023). "It frequently harbors BRAF, NRAS, or KIT mutations which influence both tumor development and treatment strategies." (PMID 37403699, 2023). "Previous studies have shown that MET, encoded by the HGFR gene, NRAS, a known RAS family oncoprotein, and NFE2L2 promote tumor growth and metastasis in HCC, and their somatic mutation can cause liver carcinogenesis." (PMID 34543520, 2022). "Concomitant driver mutations included activating mutations in classic oncogenes (e.g., KRAS, NRAS, EGFR, and PIK3CA), as well as loss-of-function mutations in tumor suppressors (e.g., BRCA1/2 and PTEN)." (PMID 36369474, 2022). "Some clinical factors, including age, TNM stage, tumour markers (CEA and CA19-9), and genetic mutations (KRAS, NRAS, and BRAF), have been reported as risk factors for colorectal metastasis in previous studies." (PMID 35296011, 2022). "As expected, livers in the control mice group looks normal, whereas livers in the mice with myr-AKT plus NRAS transfected group showed a spotty and paler appearance and were substantially enlarged, suggesting a prominent tumor development." (PMID 35912180, 2022). "To assess the co-dependency of tumour cell lines on SHOC2 and RAS, we correlated chronos scores for SHOC2 and either MRAS or HRAS, KRAS or NRAS from all 1,061 tumour cell lines in DepMap." (PMID 35768504, 2022). "We collated a total of 159 tumor samples bearing BRAF mutations, 133 with NRAS mutations, 303 with KRAS mutations, and 96 with EGFR mutations from the URMC NGS database from June 2020 to July 2021." (PMID 35627184, 2022). "It evaluates the presence of KRAS, NRAS, and BRAF mutations, nodal status, CEA/CA19-9 levels, and the modified Tumor Burden Score to predict cancer recurrence." (PMID 36428606, 2022). "RAS oncogene mutations are found in about 50% of CRC tumours with KRAS being the dominant and NRAS less frequent, while BRAF mutations are reported in 5–10% of tumours, with up to 21% reported in cohorts of patients with unresectable metastatic CRC (mCRC)." (PMID 35610367, 2022). "Mechanistically, circRanGAP1 as an oncogene promotes HCC progression by miR-27b-3p/NRAS/ERK axis, furthermore, affects the infiltration level of tumor-associated macrophages probably by sponging miR-27b-3p." (PMID 36348379, 2022). "The findings underscore the differences in the prevalence rates of HRAS, KRAS, and NRAS according to tumor anatomical site and geographical region." (PMID 35600380, 2022). "Tumor organoids harboring KRAS, NRAS, BRAF, or PIK3CA hotspot mutations exhibited a relatively higher IC50 and area under the drug response curve (AUC) for cetuximab than organoids without hotspot mutations in these genes." (PMID 34850547, 2022).
tumor (continued). "A total of 2,239 varieties of protein were identified, of which 526 types were up-regulated more than 3 times after cisplatin treatment, including tumor-driving genes such as NRAS, heat shock proteins, metabolic enzymes, and other proteins." (PMID 35431936, 2022). "The let-7 family is known for its tumor-suppressor activity (by inhibiting NRAS, HMG2A and MYC protooncogenes), and their reduced levels are typically associated with cancer stemness." (PMID 36010971, 2022). "As a point of interest, we also investigated the association between tumor budding and molecular biomarkers, such as MSI status, KRAS, and NRAS mutations." (PMID 35096426, 2022). "Monoclonal antibodies against the vascular endothelial growth factor (VEGF) or, in patients with KRAS/NRAS wild-type tumours, against the epidermal growth factor receptor (EGFR) are commonly added to chemotherapy in mCRC." (PMID 35574322, 2022). "In the CRC026 model, in which the most pronounced tumor growth inhibition was observed with AZD0156 and irinotecan, the only unique alteration identified was an NRAS Q61K mutation." (PMID 36309653, 2022). "Neat1_2 knockdown accelerated mAKT/NRAS-driven tumor development and shortened the mean survival time to 40 days, which was likely due to further reduction of Neat1_2 expression." (PMID 35547764, 2022). "No additional clinically relevant molecular aberrations were reported including NRAS mutations, BRAF mutations, HER2 overexpression, NTRK fusions, or MSI-high (MSI-H) tumor types." (PMID 36969746, 2022). "The results revealed that the downregulation of PAQR5 enriched mainly the gene set related to the upregulation of STAT3 targets, tumor formation, and poor tumor differentiation and enriched the gene set of downregulated tumor metastasis and NRAS signaling." (PMID 36119517, 2022). "It was known that KRAS/NRAS-activating mutations promote the activation of both MEK-ERK and AKT-mTOR signaling in tumor cells." (PMID 35395857, 2022). "PERSEIDA was an observational, prospective study assessing the cfDNA RAS (KRAS/NRAS) mutational status evolution in first-line, metastatic CRC, RAS wild-type (according to baseline tumor tissue biopsy) patients." (PMID 36551560, 2022). "Although both the Akt and NRAS pathways were activated in the isolated tumor clones, we observed clone-specific differences in lipid content, cancer stemness, in vivo growth, and interplay with immune cells." (PMID 35721518, 2022). "Immunolabelling of cGAS and STING in metastatic CRC was performed and further complemented by histological classification, tumour grade, and KRAS, NRAS, and BRAF mutational status of mCRC." (PMID 36612217, 2022). "NRAS (n = 3) and NF1 co-mutations (n = 2) were identified in PRKCA fusion-positive tumors, and one tumor harbored a PRKCA fusion with NF1." (PMID 35326655, 2022). "NRAS and KRAS are major members of the RAS gene family in mammals, and the proto-oncogene NRAS is abnormally highly expressed in various human malignant tumor tissues and corresponding cell lines, which can promote tumor cell invasion and metastasis." (PMID 35212617, 2022). "More importantly, we have evidence that NRAS overexpression can promote more aggressive tumor activity, such as tumor formation in mice when co-transplanted with fibroblasts." (PMID 36258226, 2022). "As a third case report, we present patient CRC-0042 (stage II) who had the following mutations detectable by sequencing of the original tumor: BRAF (N581I at 28.7% VAF), NRAS (G12V at 41.9%), and PIK3CA (E545K at 57.7%)." (PMID 36579573, 2022). "Thus, tumor cells may become less dependent on NRAS-activating mutations." (PMID 36528667, 2022). "Fusions in NTRK genes are more commonly detected in non-Lynch syndrome/MSI-H tumours as well as in wild-type BRAF, KRAS, and NRAS tumours." (PMID 35207616, 2022).
tumor (continued). "Each patient’s sex, age, genetic mutation status (BRAF, NRAS, KRAS), and MSI status based on tumor genetic profiling; location of the primary tumor; site of metastasis; and time from diagnosis to death were collected from the hospital information system." (PMID 36136880, 2022). "Our results indicated that miR-1184 promotes tumor progression by directly targeting KRAS/NRAS/HRAS in UBC." (PMID 34234808, 2021). "On average, tumour mutational burden (TMB) was 18 mutations/Mb and 34.4%, 31.3% and 25.7% of patients had structural or copy number mutations in KRAS, BRAF and NRAS, respectively." (PMID 34600575, 2021). "Comparing to the matched primary tumor, proportion of NRAS mutant clones was unchanged or higher in metastatic samples but there was no detected copy number gain of NRAS gene." (PMID 34885093, 2021). "Mutations which activate members of the RAS family (KRAS, HRAS, and NRAS) can be found in as much as 20–30% of all human tumours." (PMID 33925206, 2021). "Up until now, the association between all RAS status (exon 2, 3 and 4 of KRAS and NRAS genes) and tumor features has been investigated by few studies." (PMID 33784337, 2021). "KRAS, NRAS, and BRAF mutations in PDTOs were matched to 86.6%, 100%, and 100% of those in corresponding tumor tissues, respectively." (PMID 34359661, 2021). "The therapeutic index of pan-RAS inhibitors will depend on the effects of targeting mutant RAS (KRAS, HRAS or NRAS) oncogene addiction in tumour cells compared to the effect on normal cells when activated RAS is inhibited." (PMID 33462327, 2021). "A significant link between the NRAS rs14804 wild-type CC genotype and the early tumor stage (OR 0.215; CI: 0.061–0.757; p = 0.017) was revealed in the single-locus analysis." (PMID 34828284, 2021). "The SEER-Medicare linked database lacks information on the status of tumor mutations, including KRAS and NRAS (biomarkers of exclusion from anti-EGFR therapy), and BRAF (biomarker of poor prognosis)." (PMID 34910154, 2021). "The translational potential of this combination is strengthened by the growing identification of oncogenic mutations in HRAS, KRAS (HGNC IDs 5173, 6407), NRAS and BRAF (HGNC ID 1097) genes in SS cell lines and clinical tumor subsets." (PMID 34857011, 2021). "The approach exploits a blood biopsy to detect circulating tumour DNA (ctDNA), which can be a simple way to test for MRD, based on assessment of BRAF, NRAS, or TERT mutations that are present in more than 75% of melanoma patients’ tumours." (PMID 36284898, 2021). "To assess the independent predictive value of PDCD4 expression in tumor and stroma, we performed Cox proportional hazards analysis, which included as covariates treatment information and BRAF/NRAS mutational status." (PMID 33801444, 2021). "The KRAS/NRAS/BRAF are the downstream effectors of the EGFR signal pathway involved in tumor cell proliferation, differentiation, and invasion." (PMID 34395262, 2021). "In conclusion, the results of the present study proved an association between the NRAS rs14804 minor T allele and advanced LSCC tumor stage." (PMID 34828284, 2021). "An inferior survival after relapse for the panitumumab treated patients was observed, especially for the population with a mutation (either KRAS, BRAF, NRAS or PIK3CA), possibly due to accelerated tumour growth caused by the anti-EGFR therapy." (PMID 34253874, 2021). "This combination was found to be synergistic, and was effective in inducing tumor reduction in a nude mouse NRAS mutant xenograft tumor model." (PMID 34831002, 2021).